CD47 (CD47 molecule)
Diseases named in the same sentence as CD47 in open-access papers (continued):
Sharing a sentence is not in itself a finding about the gene and the disease.
chronic lymphocytic leukemia (12 papers, 2015 to 2026). "In this study, Santos Susin and colleagues demonstrate that a serum-stable CD47 agonist peptide is highly effective at inducing apoptosis in chronic lymphocytic leukemia B-cells and mice." (PMID 25734483, 2015). "Another study performed on hematopoietic cells showed that following CD47-triggering, B-cell chronic lymphocytic leukemia (B-CLL) cells are efficiently killed by a caspase-independent process called necrotic cell death or type III cell death." (PMID 27027430, 2016). "CD47 is expressed in many subsets of B-cell NHL including DLBCL, chronic lymphocytic leukemia (CLL), follicular lymphoma (FL), and mantle cell lymphoma (MCL)." (PMID 38966176, 2024). "Others have shown that certain CD47 antibodies, but not B6H12, directly induce apoptosis of B-cell chronic lymphocytic leukemia associated with cell shrinkage, decreased mitochondrial transmembrane potential, and phosphatidylserine externalization, but independent of apoptotic caspase activation." (PMID 26840086, 2016).
diabetes (12 papers, 2010 to 2025). "Systematic literature searches further indicated that known risk factors such as older age and diabetes are associated with increased CD47 levels." (PMID 34698067, 2021). "To further investigate the potential role of CD47 in severe COVID-19, we performed systematic literature searches on the relationship of CD47 and the known COVID-19 risk factors of “ageing”, “diabetes”, and “obesity”." (PMID 34698067, 2021). "However, further research is required to fully understand the underlying mechanisms and to explore the potential of CD47-targeted immunotherapies in the treatment of diabetes." (PMID 38125492, 2023). "Moreover, CD47 levels are elevated in groups at high risk for COVID-19, such as older individuals and individuals with hypertension and/or diabetes." (PMID 34698067, 2021). "High CD47 levels have also been reported as a consequence of hyperglycemia and diabetes, which may contribute to the high risk of severe COVID-19 in diabetic patients." (PMID 34698067, 2021). "However, obesity may at least indirectly contribute to enhanced CD47 levels as a risk factor for diabetes and hypertension." (PMID 34698067, 2021). "Uniform manifold approximation and projection (UMAP) of pancreatic cell populations and CD47 expression were derived, demonstrating clear upregulation in alpha, beta and delta endocrine cells in autoantibody-positive and diabetes samples." (PMID 40133488, 2025). "CD47 plays a role in glucose homeostasis, while glycosylation of red blood cells, as seen in diabetes, refashions membrane stiffness, perhaps triggering tendencies to phagocytosis." (PMID 38362603, 2024). "In subsequent studies, blocking CD47 showed the ability to delay the onset of overt diabetes in NOD mice, with minimal variations in insulitis scores compared to mice treated with an isotype control." (PMID 38125492, 2023). "While an understanding of how CD47 affects diabetes is continually evolving, there are several aspects worth discussing." (PMID 38125492, 2023). "Given the involvement of CD47 in diabetes pathogenesis, targeting CD47 has emerged as a potential therapeutic strategy." (PMID 38125492, 2023). "Subgroup OS analysis showed that age >60, stages III + IV, serous carcinoma, BMI >30, diabetes, and histological grade G3 combined with the high CD47 expression had a poorer prognosis." (PMID 35281519, 2022). "A PubMed search for “CD47 diabetes” produced 47 hits, nine of which reported increased CD47 levels in response to hyperglycemia and/or diabetes." (PMID 34698067, 2021). "In agreement, increased CD47 levels were detected in various cell types and tissues in rat diabetes models and diabetes patients." (PMID 34698067, 2021). "A recent study on diabetes showed that decreased CD47 expression enhanced the immune cell infiltration into islets." (PMID 33765961, 2021). "CD47 may contribute to beta cell damage during the development of diabetes and failure of islet transplant function." (PMID 40133488, 2025). "The relationship between CD47 and diabetes is an area of active research." (PMID 38125492, 2023). "Furthermore, metformin, a first line drug for type 2 diabetes mellitus, decreased the generation of stem cells through miR‐708‐mediated suppression of CD47." (PMID 31273952, 2019). "Next, we examined during the course of diabetes whether a cause-and-effect relationship exists between the overexpression of TSP1/CD47-dependent signaling and the reduction in endothelial angiogenic activity." (PMID 30720765, 2019). "Therefore, diabetes-induced increased CD47 levels may interfere with the recognition of SARS-CoV-2-infected cells by the immune system." (PMID 34698067, 2021). "Although there is no known direct impact of obesity on CD47 levels, obesity is associated with an increased risk of diabetes and other ageing-related conditions such as hypertension, which may result in elevated COVID-19 vulnerability." (PMID 34698067, 2021).
diabetes (continued). "However, data regarding TSP1 and its receptor CD47 during the course diabetes are somewhat limited." (PMID 30720765, 2019). "In Type 2 diabetes mellitus model, high lipid levels induced TSP-1-CD47 activation, and mouse treatment with anti-CD47 antibody had attenuated inflammatory response." (PMID 40231210, 2025). "Thus, the increase in CD47/IAP induced by the presence of TSP-1 leading to an increase in CD47IAP association with SHPS-1 is a potential mechanism to explain the increase in SMC proliferation and migration associated with accelerated atherosclerosis in patients with diabetes." (PMID 20689700, 2010). "CD47 expression was increased in all endocrine cells in diabetes, with the highest expression in ductal cells (this did not appreciably change with disease state)." (PMID 40133488, 2025). "Human pancreases from individuals with and without diabetes were examined for evidence of CD47 signalling." (PMID 40133488, 2025).
metastatic tumors (12 papers, 2014 to 2025). "We also performed a comparative analysis of the CD47 and PD-L1 status of tumor and immune cells in matched peripheral blood and primary and/or metastatic tumor tissue samples to investigate potential variability between the liquid and tumor biopsy." (PMID 32041353, 2020). "Here, we demonstrate, for the first time, that CD47 and PD-L1 are co-expressed on single CTCs in BC and that the incidence of CD47high and/or PD-L1high CTCs increases from early to de novo metastatic disease." (PMID 32041353, 2020). "Although we conducted the experiments primarily on mice bearing local tumors, we expect that the CD47 approach would allow the oncolytic virus to be more efficiently delivered to metastatic tumors as well by the systemic route." (PMID 30349648, 2018). "TME remodelling by engineered OMVs or IR700‐loaded engineered OMVs‐mediated photoimmunotherapy resulted in increased recruitment and activation of TAMs and the M1 phenotype, synergistically maximising antitumour efficacy with CD47 blocking therapies in primary and metastatic tumour models." (PMID 40240911, 2025). "Thus, in contrast to WT tumors, complete disruption of CD47′s inhibitory “don’t eat me” signal enables FcR-mediated phagocytosis to suppress growth of CD47 KO metastatic tumors." (PMID 35454837, 2022). "The systemic activation of antitumor macrophages following radiotherapy and CD47 blockade may be particularly important in patients with cancer who suffer from metastatic disease." (PMID 36411318, 2022). "Moreover, the detection of CD47highand/orPD-L1high CTCs numerically prevailed in de novo metastatic disease, where all CD47+/PD-L1+ CTCs presented high expression levels of both markers." (PMID 32041353, 2020). "Interestingly, the incidence of CD47+ and PD-L1+ CTCs progressively increased from early to de novo metastatic disease." (PMID 32041353, 2020). "CD47+ CTCs were evident in all settings; however, their frequency increased incrementally between patients with early, recurrent, and de novo metastatic BC (p = 0.036) and especially between early and de novo metastatic disease (p = 0.009)." (PMID 32041353, 2020). "Since the IR700@Nb289‐OMVs plus NIR irradiation and CD47 nanobody combo regimen could partially result in the complete elimination of CRC metastatic tumours, we further rechallenged the mice whose tumours had been eliminated to determine whether immune memory was generated." (PMID 40240911, 2025). "As such, in addition to support the notion that proper engagement of CD47 and SIRPα is important for establishment of metastatic tumors, this study also suggests that PC3-mCD47 cells may represent a better metastatic model than PC-3 M-LN4 for preclinical investigations." (PMID 26674012, 2015).
Obesity (12 papers, 2015 to 2025). Accumulation of substantial excess body fat. "The SIRPα-CD47 axis emerges as a potential therapeutic target for obesity and its associated complications." (PMID 40016734, 2025). "Previously, we showed that CD47 deficiency protected mice from high fat diet induced obesity, which was attributed to the increased energy expenditure driven by brown adipose tissue (BAT) activity." (PMID 36797364, 2023). "In this study, the therapeutic potential of an antisense oligonucleotide (ASO) targeting to CD47 in obesity and its-associated complications was determined in two obese mouse models (diet induced and genetic models)." (PMID 36797364, 2023). "Previous study from our lab has revealed a new role of CD47 in regulating adipose tissue function, energy homeostasis and the development of obesity and metabolic disease in CD47 deficient mice." (PMID 36797364, 2023). "As obesity is another risk factor for severe COVID-19, we also performed a PubMed search for “CD47 obesity”, which resulted in eight hits, two of which provided potentially relevant information." (PMID 34698067, 2021). "We found that cd47 deficiency protected mice from high fat diet induced obesity, which was attributed to the increased energy expenditure driven by brown adipose tissue (BAT) activity and these effects were not compromised under obese conditions." (PMID 33328190, 2020). "CD47 deficient mice challenged with a HF diet had several protective phenotypes as previously observed in TSP1 deficient mice including decreased obesity-associated inflammation and improved glucose tolerance and insulin sensitivity." (PMID 25747123, 2015). "CD47 deficiency protects mice from HF diet-induced obesity through stimulation of energy expenditure and heat production." (PMID 25747123, 2015). "In this study, we found that CD47 deficiency protected mice from HF diet induced obesity, which was associated with increased energy utilization." (PMID 25747123, 2015). "We found that CD47 deficient mice were protected from HF diet-induced obesity displaying decreased weight gain and reduced adiposity." (PMID 25747123, 2015). "In addition to protecting mice from diet-induced obesity, genetic deletion of CD47 also protects mice from natural aging-associated obesity and glucose intolerance." (PMID 36797364, 2023). "A recent report shows that CD47 deficiency may attenuate obesity and lipid accumulation in the liver of mice fed a high-fat diet (HFD) for 16 weeks." (PMID 32158445, 2020). "The authors suggested that changes in CD47 expression on the erythrocyte surface may be an adaptive response to hyperfibrinogenemia associated with obesity." (PMID 32708334, 2020). "In this study, we utilized CD47 deficient mice in a high-fat diet induced obesity model to study for the first time whether CD47 plays a role in the development of obesity and metabolic complications." (PMID 25747123, 2015). "However, to definitively demonstrate the effect of brown fat cell derived CD47 on energy metabolism in diet-induced obesity, the tissue specific CD47 deficient mice are required in future studies." (PMID 25747123, 2015). "In the current study, we determined whether TSP1 promotes obesity-associated inflammation and insulin resistance is through interaction with its receptor-CD47." (PMID 25747123, 2015). "We utilized CD47 deficient and WT mice in a diet-induced obesity paradigm." (PMID 25747123, 2015). "In this study, we utilized CD47 deficient mice in a high-fat diet induced obesity model to study for the first time whether CD47 plays a role in diet-induced obesity and its associated metabolic complications." (PMID 25747123, 2015). "Together, these data suggests that CD47 deficiency protects mice from diet-induced obesity." (PMID 25747123, 2015). "In addition, CD47 deficiency reduces obesity- associated metabolic complications including decreased systemic and adipose tissue inflammation and hepatosteatosis, and improved glucose tolerance and insulin sensitivity." (PMID 25747123, 2015).
Obesity (continued). "We have shown that CD47 deficiency protects mice from diet-induced obesity." (PMID 25747123, 2015). "Interestingly, we found that CD47 deficient mice were protected from HF diet-induced obesity displaying decreased weight gain and reduced adiposity." (PMID 25747123, 2015). "We further used genetically obese ob/ob mice to validate the strategy of blocking the SIRPa-CD47 axis in the treatment of obesity." (PMID 40016734, 2025). "CD47 is significantly upregulated in the brown adipose tissue of mice with high-fat diet-induced obesity." (PMID 40630093, 2025). "Flow cytometry revealed high CD47 expression on exosome surfaces, with minimal impact from diet-induced obesity." (PMID 40016734, 2025). "In contrast to WT mice, CD47 knockout mice exhibited anti-diet induced obesity and a reduced fat/body weight ratio." (PMID 37369998, 2023). "Accordingly, we have revealed a novel role for CD47 in regulating adipocyte function and its contribution to diet or aging-related obesity and metabolic disorders." (PMID 36797364, 2023). "In this study, the therapeutic potential of antisense oligonucleotide (ASO) targeting to CD47 in obesity and metabolic disease was determined." (PMID 36797364, 2023). "In order to assess the role of CD47 in the development of fatty liver and obesity, we compared hepatic steatosis and subcutaneous fat accumulation in WT and CD47KO mice that were chronically fed LFD (10% kcal from fat) or HFD (45% kcal from fat) for 40 weeks." (PMID 32158445, 2020). "Taken together, these data revealed a novel role for CD47 in the development of obesity and its related metabolic complications." (PMID 25747123, 2015). "In the current study, we found that obesity stimulated CD47 expression in brown adipose tissue (BAT)." (PMID 25747123, 2015). "In summary, for the first time, our studies demonstrate an important role for CD47 in regulating energy balance and the development of obesity and its metabolic complications." (PMID 25747123, 2015). "First, we found that diet-induced obesity significantly up-regulated CD47 protein levels in BAT in wild type mice." (PMID 25747123, 2015). "CD47 deficiency enhances energy expenditure by promoting brown adipocyte differentiation through upregulation of the cGMP/PKG signaling pathway, thereby alleviating obesity induced by a high-fat diet in these mice." (PMID 40630093, 2025). "CD47 ASO treatment reduced inflammation in white adipose tissue in mice with established obesity." (PMID 36797364, 2023). "Our previous studies showed that genetic deletion (global) of CD47 protected young adult mice from high fat diet-induced obesity by displaying decreased weight gain and reduced adiposity, reduced adipose tissue inflammation, and improved glucose tolerance and insulin sensitivity." (PMID 36797364, 2023). "Collectively, these studies support that CD47 might be a potential target for metabolic disorders of obesity." (PMID 36797364, 2023). "CD47 -/- mice, as well as Thbs1 -/- mice, are resistant to obesity." (PMID 33854480, 2021). "Previously, we identified a novel role of CD47 in a diet-induced obesity paradigm." (PMID 33328190, 2020). "Together, data from this study revealed a novel role for CD47 in regulation of energy homeostasis and the development of obesity, suggesting that CD47 may serve as a potential therapeutic target to combat obesity and metabolic complications." (PMID 25747123, 2015). "The results from this study suggest that CD47 may serve as a therapeutic target of obesity and its related comorbidities." (PMID 25747123, 2015). "Thus, data from our study suggest that the effect of CD47 on macrophage infiltration into adipose tissue and the development of chronic inflammation under obesity conditions is MCP1/CCR2 dependent." (PMID 25747123, 2015).
Obesity (continued). "Furthermore, targeting the SIRPα-CD47 axis can attenuate vWAT-Exos-induced metabolic disorders, providing insights into the development of potential therapeutic strategies for the future treatment of obesity and metabolic disorders." (PMID 40016734, 2025). "Previously we have demonstrated that mice lacking cd47 are leaner, exhibit increased energy expenditure, and are protected against diet-induced obesity." (PMID 33328190, 2020). "Although it has been extensively studied in cancer and ischemia, CD47 function in obesity has never been explored." (PMID 25747123, 2015). "Hence, low CD47 levels may be associated both with lower weight and increased immune recognition of virus-infected cells, but there is no direct evidence suggesting that obesity may also directly increase CD47 expression." (PMID 34698067, 2021). "However, whether CD47 regulates BAT function and contributes to diet-induced obesity is unknown." (PMID 25747123, 2015).
oral squamous cell carcinoma (12 papers, 2019 to 2026). "In this study, we investigated whether GV1001 modulated CD47 expression and enhanced antitumor immunity in oral squamous cell carcinoma (OSCC)." (PMID 41977514, 2026). "Similarly, one report showed that silencing CD47 decreased MYC expression in oral squamous cell carcinoma, which indicates that CD47 can increase MYC expression." (PMID 36966168, 2023). "Interestingly, another report shows that silenced CD47 reduces Myc expression in oral squamous cell carcinoma 27, which suggests that CD47 could increase Myc expression." (PMID 34512146, 2021). "Therefore, we believe that CD47 and HSPA5 have a feedback loop in OSCC cell lines, and suggest that CD47 mediates cancer progression through the HSPA5 signaling pathway in oral squamous cell carcinoma." (PMID 35678681, 2022).